IL6 (interleukin 6)
Diseases named in the same sentence as IL6 in open-access papers (continued):
Sharing a sentence is not in itself a finding about the gene and the disease.
COVID-19 (continued). "Both IL-6 and TNF-α are known to be the main cytokines involved in severe symptoms’ onset in COVID-19 patients, and to be downstream of the TLR4 signalling pathway." (PMID 34564408, 2021). "Plasma proteins associated with neutrophil and ROS responses including IL8, CXCL10, and EN-RAGE primarily derived from activated neutrophils, IL6, and PRDX1 were also elevated in lung tissue from patients with COVID-19." (PMID 34648357, 2021). "This sex-specific anti-inflammatory effect resulted from the greater reduction of IL-6 and TNF-α, was possibly crucial to COVID-19 severity." (PMID 34373739, 2021). "The results indicated that there were positive correlations between renal dysfunction with IL-6 and CRP in COVID-19 patients." (PMID 33557785, 2021). "In conclusion, MHD patients with COVID-19 who experienced unfavorable outcome had more elevated CRP, IL6 and fibrinogen as well as procalcitonin levels at various points compared to survivors." (PMID 33967613, 2021). "Higher levels of IL-6 and TNF-alpha were found in the COVID-19 group compared to other infections and control groups (p = 0.014 and p = 0.001, respectively)." (PMID 34578450, 2021). "As for wave 1, significant differences and increasing trends of IL-1β, IL-1ra, IL-2, IL-6, IL-8, IL-10, GM-CSF, IFN-γ, IP-10, were observed in the three groups (Controls ≤ Mild COVID-19 ≤ Severe COVID-19)." (PMID 34675240, 2021). "The activation of this pathway results in the release of pro-inflammatory cytokines including IL-6 and TNF-α, which are vastly elevated ones in severe COVID-19 patients." (PMID 35401158, 2021). "Among these cytokines, serum levels of IL1-β, IL-6, IL-8, and TNF-α were found to be significantly increased in the critical COVID-19 patients relative to mild patients." (PMID 34276659, 2021). "After 6 or 24 h of honeysuckle or Huangqi treatment, the cell medium was collected to quantify the secretion level of IL-6 and TNF-α, two of the most abundantly detected cytokines in COVID-19 patients’ plasma." (PMID 35401158, 2021). "For example, in intensive care unit (ICU) COVID-19 patients there is evidence of a reduction in serpin family A member 12 (SERPINA12) and dipeptidyl peptidase 4 (DPPD-4), which are down regulated by IL-6." (PMID 34361021, 2021). "In agreement, we found enhanced production of IL-6 and TNF-α by monocytes and NK cells of COVID-19 patients once treated with the recombinant human Gal-9 in vitro." (PMID 33947753, 2021). "According to existing data, IL-6 surpasses CRP and other inflammatory indicators in predicting respiratory failure in COVID-19." (PMID 34966605, 2021). "In this study, we found that inflammatory biomarkers (IL-6 and TNFα) and GAC markers (Hyal and SDC1) were elevated in hospitalized COVID-19 patients compared with HC." (PMID 34792686, 2021). "Our previous work has demonstrated that serum concentrations of IL-6 are negatively correlated with circulating CD4+ and CD8+ T cell counts in COVID-19 patients, but little is known about the source of IL-6." (PMID 33995382, 2021). "The inhibition of IL-6 signaling using tocilizumab decreased PAI-1 production and alleviated the clinical symptoms in severe COVID-19 patients." (PMID 34454610, 2021). "CXCL10, interleukin (IL-15) and interferon (IFN-g) are increased after a COVID-19 vaccination with a BNT162b2 mRNA (Pfizer/BioNTech) vaccine and are enriched by tumor necrosis factor alpha (TNF-α) and IL-6 after the second vaccination." (PMID 34835155, 2021). "In another study of COVID-19 patients who needed ICU hospitalization, a remarkable CD14+CD16+ monocyte levels that also produce IL-6 were noticed." (PMID 33859644, 2021). "These subjects were older and showed significantly lower 25OHD levels, lymphocytes and platelets levels and higher IL-6, C-reacting protein (CRP), LDH and neutrophil levels than COVID-19 patients who survived." (PMID 34126960, 2021).
COVID-19 (continued). "Significantly elevated concentrations of C-reactive protein (CRP) produced as a result of macrophage stimulation by IL-1β, IL-6, or TNF-α have also been observed in COVID-19 patients." (PMID 33466589, 2021). "Myeloid hyperinflammation causing lung and peripheral tissue damage via secretion of inflammatory cytokines such as IL-6 and tumor necrosis factor (TNF) in COVID-19 has been reported and in our analysis were primarily expressed by tissue rather than blood MPs." (PMID 33879890, 2021). "However, further studies with blood sampling from COVID-19 patients should be performed to measure sNRP1 levels and to study the correlation between sNRP1 and COVID-19 risk factors (for example, CRP, d-dimer and IL6) in response to glycemic control in order to elucidate the mechanism." (PMID 34248841, 2021). "Studies have shown that patients with severe COVID-19 characterised by a “cytokine storm” inexorably exhibit high levels of IL-6 and TNF-α in serum, and IL-6 or TNF-α antagonist seem to be very promising for severe COVID-19 cases." (PMID 34059076, 2021). "Hospitalized COVID-19 patients with acute disease showed significantly higher levels of inflammatory markers (CRP, IL-6) compared to convalescent patients and healthy controls as sign of inflammation due to acute viral infection." (PMID 34835130, 2021). "More than half of ARDS in all COVID-19 patients manifested macrophage activation syndrome with high levels of TNF and IL-6 in the circulation." (PMID 33907514, 2021). "In our study, we found that the core pathogenesis target of COVID-19 was TNF, while the secondary pathogenesis targets included IL6, IL10, and IL2 cytokines." (PMID 34731090, 2021). "Different from recent studies showing remarkably elevated levels of IL-6, IL-10, and IFN-γ in severe COVID-19 patients, we only observed notably increased levels of IL-6 in severe patients." (PMID 33390771, 2021). "Raised neutrophil-lymphocyte ratio, mean platelet volume, IL-6, D-dimer, serum ferritin, LDH, and CRP were important prognostic markers in determining the severity of COVID-19." (PMID 34966605, 2021). "In this study, we investigated the effect of pre-analytical sample handling variations on levels of COVID-19-relevant cytokines IFN-γ, IL-10, IL-12p70, IL-17A, IL-6 and TNF-α." (PMID 34289718, 2021). "COVID-19 patients are also reported to show CD4+ lymphopenia; CD8+ lymphopenia; and higher levels of cytokines such as interleukin (IL)-6, IL-10, and tumor necrosis factor alpha (TNF-α)." (PMID 34360684, 2021). "As an immune response to viral infection, proinflammatory cytokines and chemokines such as IL-6, IL-1, IL-18, TNF, granulocyte-colony stimulating factor (GCS-F) have been detected at high levels in COVID-19 patients." (PMID 34590796, 2021). "There is increasing evidence that cytokines such as IL-6, IL-1 beta, IFN-gamma and TNF-alpha play important role in pathogenesis of cytokine storms in COVID-19." (PMID 34804738, 2021). "This study determined that the IL-6, NEUT, and NK cell combination, which showed good prediction of COVID-19, had 93% sensitivity and 100% specificity in the training data." (PMID 34220307, 2021). "Several studies have suggested the role of IL-6 in the pathogenetic mechanisms of COVID-19: when SARS-CoV-2 infects the respiratory tract, it induces a release of pro-inflammatory cytokines, including interleukin (IL)-1beta and IL-6." (PMID 33975613, 2021). "At the same time, valuable clues for the treatment of COVID-19 can probably be found via going through application of IL-6 blockers in rheumatoid diseases and JIA, which are more mature fields in IL-6 inhibitors." (PMID 37287491, 2021).
COVID-19 (continued). "TMPRSS2 is an enzyme that primes the spike S protein of the SARS-CoV-2 virus to promote virus entry, IL6 and TNF are pro-inflammatory cytokines that are found generally elevated in severe COVID-19 patients." (PMID 34109284, 2021). "Infrared light therapy has been shown to decrease TLR4-dependent induction of IL-6, IL-8, TNF-α, INF-α, and INF-β in COVID-19 hyperinflammation." (PMID 34835108, 2021). "Interferons are downstream inflammatory products of IL-1, IL-6, and tumor necrosis factor (TNF), key inflammatory molecules released by immune cells in multiple tissues affected by COVID-19." (PMID 34512253, 2021). "The hyperinflammatory response in COVID-19 is characterized by elevated levels of serum TNF-α, IL-6, and to a lower level IL-1A since this cytokine has a short serum half-life." (PMID 33995033, 2021). "It has been shown that capillary leak, the major factor deteriorating lung function in patients with COVID-19, is driven by TNF-α, IL-1A, and IL-6 inflammatory cytokines." (PMID 33995033, 2021). "Consistent with such an important role for inflammation in COVID-19, is the finding that both IL-6 and CRP are strong markers of COVID-19 disease activity." (PMID 33692801, 2021). "In particular, the cytokines IL-6, IL-8, CXCL9, and CXCL10 (IP-10) were identified as putative prognostic disease progression markers for COVID-19." (PMID 34759825, 2021). "It is estimated that 10–15% of patients with severe COVID-19 progressed to ARDS triggered by cytokine storm, due to overproduction of IL-6, IL-8, IL-10, IL-17, and TNF-α." (PMID 34445556, 2021). "LUS was significantly correlated with COVID-19 biomarkers as C-reactive protein (CPR; p = 0.011), interleukin-6 (p = 0.013), and pro-adrenomedullin (p = 0.02), and inversely related to arterial oxygen saturation (p = 0.004)." (PMID 35127744, 2021). "Progranulin showed high discriminative power to differentiate bacterial CAP from COVID-19 (sensitivity 0.91, specificity 0.94, AUC 0.91 (CI = 0.8–1.0) and performed significantly better than PCT, IL-6 and CRP." (PMID 34476621, 2021). "Elevated IL6 levels have been discovered in ARDS and lung transplantation complications, and have already been shown to be elevated in COVID-19 patients." (PMID 33737684, 2021). "IL-6 upregulates hepatic CRP production, thus suggesting the plausibility of the clinical use of this inflammatory biomarker as a prognosis predictor for COVID-19 patients." (PMID 34454452, 2021). "The levels of IL-6 and GDF-15 in sepsis were statistically significantly higher than those in COVID-19 on day 1 to days 6-8, and on day 1 and days 2-3, respectively." (PMID 35095877, 2021). "In our virtual cohort, we found that severe COVID-19 responses were tightly correlated with a delay in the peak IFN concentration and that a large increase in IL-6 was the dominant predictor of CD8+ T cell depletion." (PMID 34260666, 2021). "Compared to those alive, all the patients who died from COVID-19 had increased levels of TNF-α, IL-2R, IL-6, IL-8, and IL-10 tested on admission." (PMID 33735106, 2021). "Since siltuximab neutralizes IL-6, it has been approved by FDA for phase III clinical trials for hospitalized patients suffering from COVID-19-related acute respiratory distress syndrome (ARDS)." (PMID 34885798, 2021). "Both IL-6 and TNF-α are found in patients with COVID-19 and are responsible for pathological injury." (PMID 34360684, 2021). "The functional analysis of these two gene clusters further illustrated the effects of biochanin A on interleukin-6 production and cytokine-cytokine receptor interaction in CRC/COVID-19 pathology." (PMID 34931923, 2021). "Its key compounds including quercetin, kaempferol, 7-O-methylisomucronulatol, baicalein, and formononetin target IL6, MAPK8, PTGS2, PTGS1, and NCOA2 to regulate multiple signal pathways of TCM and play a therapeutic role in the recovery period of COVID-19." (PMID 34335247, 2021).
COVID-19 (continued). "Although IL-1β, IL-6, and TNFα are well-established to influence nociceptive hypersensitivity, the possibility that additional or alternative mediators may also be driving nociceptive sensitivity in patients with COVID-19 cannot be discounted, especially in severe and critical infection." (PMID 33458558, 2021). "The soaring IL-6 levels during SARS-CoV-2 infection activate CRP, another inflammatory culprit to COVID-19-based multiple systemic disorders and pneumonia." (PMID 33946736, 2021). "There was a significantly lower proportion of patients with severe COVID-19 in MAFLD patients with normal IL-6 levels, than in those with elevated IL-6 levels (8.70% vs. 47.83%, p = 0.003)." (PMID 33763027, 2021). "There are laboratory markers available to measure the extent of injury from COVID-19, such as CK-MB, CRP, IL-6 and ferritin." (PMID 33078963, 2021). "The patients who recovered from COVID-19 had significantly lower plasma levels of KYN, CRP, IL-6, ferritin, NTproBNP, cTnT, and creatinin." (PMID 34943063, 2021). "Increased levels of proinflammatory cytokines, including IL-2, IL-6, IL-7, IL-10, IFNγ, and TNF-α, are commonly observed in patients with severe COVID-19." (PMID 34001144, 2021). "The serum of patients with COVID-19 contains cytokines like TNF- alpha and IL-6, which obstruct mitochondrial oxidative phosphorylation, ATP production, and produce ROS in the cell." (PMID 34360945, 2021). "The results showed that in the lung tissues of patients with COVID-19, CyPA had strong positive correlations with CD68, CCL2, and IL-6." (PMID 34564690, 2021). "Both IL-1 and IL-6 are critical in regulating CRP levels, which has been found to be prognostic with regard poor outcome in patients with COVID-19." (PMID 34169381, 2021). "Given the pivotal role of IL-6 in COVID-19 induced cytokine storm, it is attractive to target hyperinflammation during SARS-CoV-2 infection via the blockage of IL-6." (PMID 34001244, 2021). "In the present study of 160 consecutive critically ill COVID-19 patients with moderate to severe ARDS, IL-6, serum albumin, and D-dimer at admission to ICU, accompanied by chest CT severity score, were marked as independent predictors of mortality." (PMID 33968298, 2021). "It is known that in severe cases of COVID-19, patients showed increased serum cytokine levels of IL-2, TNFα, IL-1β, IFNγ, MCP-1, MIP1α, IL-10, and IL-6." (PMID 34244584, 2021). "Our results suggest that IL-6, which is the key cytokine located upstream of the inflammatory cytokine cascade, increases prior to ARDS in critical COVID-19 patients, followed by an increase in acute-phase protein levels, such as CRP." (PMID 34441262, 2021). "We found that — in contrast, for example, to IL-6 — plasma SPP1 and S100A12 remained significantly higher than normal for at least 10 weeks after infection clearance in the post–COVID-19 convalescent phase." (PMID 34143756, 2021). "Furthermore, studies suggest that the pathophysiology of COVID-19-related AKI is similar to that of sepsis-associated AKI, as the majority of damage within the kidneys is due to the hemodynamic and immunologic effects of the infection, as supported by the increased levels of CRP and Il-6." (PMID 34209289, 2021). "Previous studies have reported abnormal levels of IL-2, IL-6, IL-7, IL-10, CRP, and tumor necrosis factor-α in COVID-19 patients." (PMID 34242179, 2021). "One of the most prominent characteristics of severe COVID-19 is the massive release of a wide range of cytokines, such as TNF, interferon γ (IFN-γ) and IL-1, IL-6, and IL-18, which characterizes the cytokine storm observed in SARS-Cov-2 infected patients." (PMID 34977191, 2021). "Our findings of raised TNF-α and IL-6 levels after SARS-CoV-2 infection are comparable to other research and are consistent with the cytokine storm described in COVID-19." (PMID 34884175, 2021).
COVID-19 (continued). "During the period of COVID-19, HLJDD was also found to play a therapeutic role in COVID-19 through regulating multiple signaling pathways based on targeting genes such as IL6, IL10, MMP9, NOS2, VEGF, and TGFβ1." (PMID 35127697, 2021). "In consistence with previous observations, IL-6, CCL2, CXCL2, CXCL10, and IL-8 were significantly elevated in COVID-19 samples." (PMID 34103487, 2021). "Within this cohort of severe COVID-19 patients admitted in ICU, HMGB1, and IL-6 plasma concentrations measured at ICU admission were highest in patients with a fatal course of the disease." (PMID 33939645, 2021). "We detected minimal TNF-mediated or IL-6-mediated JAK–STAT signaling activation in circulating monocytes and DCs, but this was upregulated by COVID-19 BAL MPs." (PMID 33879890, 2021). "IL-2 was lower in COVID-19 patients than in healthy individuals, while IL-4, IL-6, CCL2, IFN-γ, and TNF-α were higher in COVID-19 patients than in healthy individuals." (PMID 34489974, 2021). "It has been reported that the levels of many inflammatory markers, such as interleukin (IL)-6, IL-7, monocyte chemoattractant protein (MCP)-1, and macrophage inflammatory protein (MIP)-1α, are elevated in COVID-19 patients." (PMID 34925252, 2021). "Increased cytokine secretion, including IL-2, IL-4, IL-6, IL-10, tumor necrosis factor (TNF)-α, and IFN-γ, in COVID-19 patients has been reported." (PMID 33445583, 2021). "In COVID-19, the spike protein of SARS-CoV-2 induces the production of IL-6 by both macrophages and lung epithelial cells." (PMID 35095877, 2021). "These pathways include processes crucial for COVID-19 severity including T cell mediated immunity, macrophage activation and cytokine production (IL1, IL6, IL8 and TNF, among others)." (PMID 34075090, 2021). "For example, tocilizumab (a monoclonal antibody against IL6) and convalescent plasma therapy (CPT) reduced IL6 concentrations, controlled and relieved inflammation, and managed the cytokine storm in COVID-19 patients." (PMID 34975885, 2021). "One of the most important findings of this study was that COVID-19 patients display strong expansion of PMN-MDSC and Mo-MDSC, the latter of which contribute mostly to IL-6 production in severe COVID-19 patients." (PMID 33692788, 2021). "COVID-19 is also characterized by a “cytokine storm” with increased levels of pro-inflammatory cytokines in the blood, such as IL-1β, TNF-α, IL-6, IL-12, and we detected increased IL-1β, IL-6, IL-12, IL-23, and IL-27 in the serum following ORN06 aspiration." (PMID 33481950, 2021). "Pro-inflammatory cytokines and chemokines (IL-6, IL-8, TNF-α, IL-1β) are differentially expressed in COVID-19 patients according to severity." (PMID 34320031, 2021). "Among the molecules involved in this immune derangement, there are adipocytokines, including leptin, cytokines, such as TNF-alpha, IL-6, IL-12, Il-1b, MCP-1, and nitric oxide, which have also been correlated with worse COVID-19 clinical outcomes." (PMID 34959805, 2021). "Via the TLR9 pathways, a plethora of inflammatory mediators and cell types can be triggered such as interleukin-6 (IL-6) and tumor necrosis factor (TNF)-α in severely ill patients with COVID-19." (PMID 36303774, 2021). "A multivariable analysis of patients’ first samples associated an increase of CCL2, IL-15, secreted tumor necrosis factor receptor superfamily member 1A sTNFRSF1A, IL-6, MMP-9, IL-2, or IL-10 with COVID-19 mortality." (PMID 33800947, 2021). "In order to determine the relationship between IL-33 and proinflammatory mediators in all stages of COVID-19, we analyzed the ratio of the systemic values of IL-33 with the values of TNF-α, IL-1β, IL-6, IL-12, and IL-23." (PMID 34917631, 2021). "Plasma IL-6 and TNF-α levels were significantly higher in COVID-19 patients and active AOSD patients than in HC." (PMID 34367188, 2021). "Thus, IL-6 might be a surrogate biomarker in hypertensive COVID-19 patients." (PMID 34806090, 2021).